KRT80 (keratin 80)
Synonyms: KB20
Tractability: PROTAC: ubiquitination databases record sites on it; its protein half-life has been measured.
Gene: Protein-coding gene on chromosome 12 (52,168,996 to 52,192,014, reverse strand). Ensembl gene ENSG00000167767.
Subcellular location (Human Protein Atlas): Intermediate filaments
Pathways (Reactome):
Developmental Biology: Formation of the cornified envelope; Keratinization
Gene Ontology:
Molecular function: protein binding; structural constituent of skin epidermis
Biological process: intermediate filament organization; keratinization
Cellular component: intermediate filament cytoskeleton; cytosol; keratin filament
Genetic constraint (gnomAD): Loss-of-function variants: 36 observed, 49.81 expected, observed/expected ratio (o/e) 0.72, 90% interval 0.55 to 0.95. The upper end of that interval is the gene's LOEUF score, 0.95, which puts it in group 4 of 6, group 1 being the genes least tolerant of losing a copy. Missense variants: 565 observed, 585.15 expected, observed/expected ratio (o/e) 0.97, 90% interval 0.9 to 1.03. Synonymous variants: 235 observed, 246.52 expected, observed/expected ratio (o/e) 0.95, 90% interval 0.86 to 1.06.
Homologues: Orthologues: chimpanzee KRT80 (99% identical), macaque KRT80 (97% identical), guinea pig KRT80 (87% identical), rat Krt80 (86% identical), mouse Krt80 (86% identical), pig KRT80 (85% identical), dog KRT80 (77% identical), rabbit KRT80 (65% identical), tropical clawed frog slc22a23 (35% identical). Paralogues in human: KRT75 (45% identical), KRT5 (44% identical), KRT76 (44% identical), KRT6A (43% identical), KRT6C (43% identical), KRT8 (43% identical), KRT6B (43% identical), KRT3 (43% identical), KRT4 (42% identical), KRT79 (41% identical), KRT2 (41% identical), KRT84 (41% identical), and 56 more.
Diseases named in the same sentence as KRT80 in open-access papers:
KRT80 is named in the same sentence as 32 diseases in open-access papers, as found by Europe PMC text mining. Sharing a sentence is not in itself a finding about the gene and the disease. The quoted sentences say what the papers report.
breast carcinoma (13 papers, 2017 to 2025). "Recently, abnormal KRT80 expression has been found in colorectal, gastric, and breast cancer, where it plays an important role in tumor development and progression 11-14." (PMID 34659572, 2021). "KRT80 is overexpressed in colorectal, gastric, and breast cancers, and esophageal squamous cell carcinoma 11-14, 28, but has not been studied in ovarian cancer." (PMID 34659572, 2021). "SREBP1 drives the cytoskeletal changes and invasion of endocrine-resistant ERα breast cancer cells by Keratin-80 upregulation." (PMID 31861383, 2019). "A recent study established a model depicting that long-term aromatase inhibitors (AI) treatment promotes constitutive activation of SREBP1, which leads to reactivation of ERα and cytoskeletal rearrangements via Keratin-80 and promotes the invasive phenotype of breast cancer cells." (PMID 31861383, 2019). "Keratin 80 (KRT80), an epithelial keratin, has been described as a factor in endocrine-resistant ER breast cancer that promotes cytoskeletal changes and invasive conduct." (PMID 35110531, 2022). "Real-time quantitative PCR validation of RNA-seq data was done for IDH2, ID1, KRT80, and CALCR genes both in circNFATC3 silenced MDA-MB-231 breast cancer cells and SK-OV-3 ovarian cancer cells." (PMID 33816459, 2021). "Totally 15 breast cancer risks genes were obtained (Benjamini & Hochberg FDR < 0.05) and 6 of them (FAM84B, AAGAB, RPS25, SH3BP4, KRT80, TANK) showed the most significant correlation with the patient survival." (PMID 28621677, 2017). "Despite TAD dynamics, only few keratins within the type II-keratin TAD were transcriptionally reprogrammed in AI-resistant cell lines, with KRT80 being the only member which was consistently upregulated in all LTED models, including LTED-derivatives from a different breast cancer cell line (T47D)." (PMID 31073170, 2019).
gastric cancer (13 papers, 2021 to 2025). A primary or metastatic malignant neoplasm involving the stomach. "Via the PI3K/Akt pathway, the circPIP5K1A/miR-671-5p/KRT80 axis helps GC progression, according to a study of gastric cancer linked to KRT80." (PMID 35110531, 2022). "KRT80 has been implicated in the evolution of breast and gastric cancers." (PMID 36248424, 2022). "Studies have reported that OTUB2 facilitates cancer metastasis via activating YAP and TAZ and enhances the proliferation of gastric cancer cells by deubiquitinating KRT80." (PMID 40296903, 2025). "KRT80 could distinguish between good and poor survival outcomes in gastric cancer (GC) patients and is an independent risk factor for the prognosis of patients with ovarian cancer." (PMID 40647481, 2025). "Recent evidence in regard to gastric cancer shows that circPIP5K1A functions as a competing endogenous RNA by sponging miR-671-5p, thereby relieving the repression of KRT80 and activating PI3K/AKT signaling to promote tumor progression." (PMID 40647481, 2025). "In colorectal cancer, gastric cancer, and lung adenocarcinoma, KRT80 has been identified as a potential biomarker." (PMID 40428339, 2025). "In several tumor types, KRT80 is upregulated, contributing to malignant oncological behaviors, such as those seen in colon cancer, gastric cancer, ovarian cancer, and breast cancer 9-14." (PMID 38495507, 2024). "Additional studies have suggested that OTUB2 stabilizes KRT80 by deubiquitinating it, consequently promoting gastric cancer progression." (PMID 38495507, 2024). "We constructed a subcutaneous xenograft model to examine the effects of OTUB2 and KRT80 on the proliferation and tumorigenesis of gastric cancer cells in vivo." (PMID 35110531, 2022). "We then conducted cell proliferation experiments in vitro and discovered that both OTUB2 and KRT80 can promote the proliferation of gastric cancer cells." (PMID 35110531, 2022). "Once KRT80 protein expression was restored, gastric cancer cells' growth ability was restored concurrently." (PMID 35110531, 2022). "Keratin 80 facilitates the viability, proliferation, and migration of gastric cancer cells and inhibits cell apoptosis." (PMID 36685817, 2022). "The results indicate that OTUB2 promotes the growth and proliferation of gastric cancer cells in vivo by specifically deubiquitinating the stability of KRT80." (PMID 35110531, 2022). "To investigate the function of OTUB2 and KRT80 in gastric cancer cells, we conducted a western blotting analysis of four gastric cancer cell lines first." (PMID 35110531, 2022). "In gastric cancer, overexpression of the circular RNA CircPIP5K1A induced expression of KRT80 and activated the PI3K/AKT pathway via miR-671-5p adsorption." (PMID 36232922, 2022). "Similarly, knockdown of KRT80 expression has been demonstrated to suppress tumor growth and chemoresistance in gastric cancer." (PMID 40428339, 2025). "OTUB2 regulates KRT80 stability via deubiquitination and promotes gastric cancer growth." (PMID 39605891, 2024). "We then investigated the relationship between the two and discovered that OTUB2 was indeed capable of stabilizing KRT80 by specifically deubiquitinating it via Lys-48 and Lys-63, thereby activating the Akt pathway and thus promoting gastric cancer cell proliferation." (PMID 35110531, 2022). "Moreover, when OTUB2 expression was decreased, KRT80 protein expression was decreased, inhibiting gastric cancer cells' growth capacity." (PMID 35110531, 2022). "Given that OTUB2 promotes gastric cancer growth and proliferation by positively regulating the activation of the PI3K/AKT signaling pathway via KRT80, we believe that KRT80 also has clinical effects similar to OTUB2." (PMID 37211956, 2023). "Then we developed OTUB2-knockdown AGS and KRT80-knockdown AGS cells and KRT80-overexpression MKN45 to investigate OTUB2 and KRT80 in gastric cancer with the aid of lentivirus technology." (PMID 35110531, 2022).
gastric cancer (continued). "Taken together, both OTUB2 and KRT80 positively promote growth and proliferation in gastric cancer cells in vitro, and OTUB2 also specifically regulates the expression of KRT80 proteins." (PMID 35110531, 2022). "circPIP5K1A can activate KRT80 and the PI3K/AKT pathway to promote gastric cancer by regulating miR-671-5p." (PMID 33841499, 2021). "Moreover, the interaction between PRKDC and KRT80 protein accelerated invasion in colon cancer 9, and OTUB2 influenced KRT80 stability through deubiquitination, promoting the malignancy of gastric cancer." (PMID 38495507, 2024). "Multiple immunofluorescence (IF) staining analysis was performed to evaluate OTUB2 and KRT80 expression in a tissue microarray (TMA) consisting of 90 cases of primary gastric cancer with different tumor differentiation and paired adjacent normal tissues." (PMID 35110531, 2022). "And the expression of OTUB2 and KRT80 proteins was not 100% consistent in gastric cancer and paired adjacent normal tissues." (PMID 35110531, 2022). "This is consistent with KRT80 protein expression in gastric cancer, but not with KRT80 mRNA expression." (PMID 35110531, 2022).
colorectal cancer (10 papers, 2009 to 2025). A primary or metastatic malignant neoplasm that affects the colon or rectum. "This study investigated the role of KRT80 in the prognosis of colorectal carcinoma (CRC) and the underlying mechanisms involved in CRC migration and invasion." (PMID 30262880, 2018). "KRT80 was previously documented to facilitate the colorectal cancer cell proliferation and invasion through the AKT pathway and interacted with PRKDC." (PMID 36248424, 2022). "Although KRT80 has been reported to play an oncogenic role in colorectal carcinoma and endocrine-resistant breast cancer, the role of KRT80 in HNSC remains unexplored." (PMID 35965679, 2022). "KRT80 is a type II keratin that has emerged as an oncogenic driver in several malignancies, yet its involvement in colorectal cancer (CRC) remains unclear." (PMID 40647481, 2025). "Although KRT80 may act as a mediator of oncogenic signaling, the molecular mechanisms in colorectal cancer (CRC) development still need to be evaluated." (PMID 40647481, 2025). "KRT80 could interact with protein kinase, DNA-activated, catalytic polypeptide in colorectal cancer cells." (PMID 38241178, 2024).
ovarian carcinoma (10 papers, 2021 to 2025). A malignant neoplasm originating from the surface ovarian epithelium. "In the cBioPortal database, 587 cases of ovarian cancer with KRT80 gene changes were analyzed, and the mutation rate of KRT80 was 4.6%, including 2.39% amplification, 0.17% deep deletion, and 2.04% high mRNA in TCGA (Firehose Legacy)." (PMID 34659572, 2021). "In summary, we determined that KRT80 is significantly overexpressed in ovarian cancer and is associated with a poor prognosis." (PMID 34659572, 2021). "KRT80 may have applications as a diagnostic and prognostic indicator for ovarian cancer, and may represent a therapeutic target for novel targeted treatment regimens." (PMID 34659572, 2021). "KRT80 is an independent risk factor for the prognosis of patients with ovarian cancer." (PMID 34659572, 2021). "Elevated KRT80 expression has been previously identified as an independent prognostic factor and potential therapeutic target in ovarian cancer." (PMID 40428339, 2025). "For instance, in ovarian cancer, KRT80 overexpression promotes cell proliferation, invasion, and migration, and is associated with unfavorable patient prognosis." (PMID 40647481, 2025). "The identification of potential targets such as HIF1A and KRT80 holds promise for the development of innovative therapeutic strategies against drug-resistant ovarian cancer." (PMID 40428339, 2025). "In ovarian cancer, overexpression of KRT80 induced the expression of genes related to epithelial–mesenchymal transition and activated both MEK and ERK." (PMID 36232922, 2022). "A recent study found that KRT80 accelerates ovarian cancer cell growth, cycle transitions from G1 to S phase, migration, and invasion through activating MEK/ERK pathway." (PMID 36248424, 2022). "We further explored the relationship between the expression of KRT80 and the occurrence and development of ovarian cancer, revealing its regulatory pathways, transcription factors, and upstream miRNAs." (PMID 34659572, 2021). "The high expression rate of KRT80 in the ovarian cancer group (56.86%, 58/102) was significantly higher than that in the normal and benign (7.14%, 1/14) groups (P < 0.001)." (PMID 34659572, 2021). "KRT80 is expected to play an important role in the early diagnosis, prognosis evaluation, and clinical treatment of ovarian cancer in the future, and is a promising regulatory gene for ovarian cancer." (PMID 34659572, 2021). "Taken together, KRT80 plays an important role in the development of various tumors, and should be studied further in ovarian cancer." (PMID 34659572, 2021). "In the present study, we identified the high expression of KRT80 in ovarian cancer tissue by immunohistochemical analysis, and further confirmed this result using cancer databases." (PMID 34659572, 2021). "In the present study, we verified that the expression of MEK/ERK signaling pathway proteins were dysregulated in ovarian cancer cells with overexpression or knockdown of KRT80." (PMID 34659572, 2021). "To further explore the mechanisms by which KRT80 affects the malignant biological behavior of ovarian cancer cells, we performed pathway enrichment analysis in the GSEA database and found that KRT80 is related to the MAPK signaling pathway." (PMID 34659572, 2021). "Single-factor Cox regression analysis showed that the expression of KRT80, FIGO stage, and lymph node metastasis were risk factors for the prognosis of ovarian cancer (P < 0.01)." (PMID 34659572, 2021). "KRT80 overexpression promotes the proliferation of ovarian cancer cells, the transition from G1 phase to S phase, invasion, and migration." (PMID 34659572, 2021). "The positive expression rate of KRT80 in the ovarian cancer group (79.41%, 81/102) was significantly higher than that in the normal (26.67%, 4/15) and benign (28.57%, 4/14) groups (P < 0.001)." (PMID 34659572, 2021).
ovarian carcinoma (continued). "In the present study, overexpression and knockdown of KRT80 promoted the proliferation of ovarian cancer cells, the change from G0/G1 phase to S phase, and promoted the invasion, migration, and progression of EMT in ovarian cancer cells." (PMID 34659572, 2021). "We also studied the effect of KRT80 overexpression and knockdown on the malignant biological behavior of ovarian cancer cells in vitro." (PMID 34659572, 2021). "ETS1 mRNA was positively correlated with KRT80 mRNA in 379 cases of ovarian cancer (P < 0.05, r = 0.161)." (PMID 34659572, 2021). "The positive expression rate of KRT80 in the ovarian cancer group (79.41%, 81/102) was also higher than that in ovarian borderline group (75.00%, 12/16), but the difference was not statistically significant (P > 0.05)." (PMID 34659572, 2021). "This confirms that KRT80 promotes the malignant biological behavior of ovarian cancer cells by activating the MEK/ERK signaling pathway." (PMID 34659572, 2021). "In the present study, we examined the expression of KRT80 in ovarian tissue, and studied the relationship between KRT80 expression and clinicopathologic parameters and prognosis of ovarian cancer." (PMID 34659572, 2021). "In the GEPIA database, the expression of KRT80 in 426 ovarian cancer patients was significantly higher than that in 88 normal ovarian tissue samples (P < 0.05)." (PMID 34659572, 2021). "Cell lines overexpressing KRT80 and with KRT80 knockdown were established to study its effect on the malignant behavior of ovarian cancer cells." (PMID 34659572, 2021). "The expression of KRT80 protein in ovarian cancer cell lines and normal ovary epithelial cells was detected by western blotting." (PMID 34659572, 2021). "In order to further explore the molecular mechanism and biological function of KRT80 in ovarian cancer, we analyzed it." (PMID 34659572, 2021). "In the present study, we confirmed that KRT80 promotes ovarian cancer progression through the MEK/ERK pathway." (PMID 34659572, 2021). "The high expression rate of KRT80 in the ovarian cancer group (56.86%, 58/102) was also higher than that in the ovarian borderline group (31.25%, 5/16), although this was not statistically significant (P > 0.05)." (PMID 34659572, 2021). "In the present study, Kaplan-Meier analysis showed that KRT80 expression was correlated with the prognosis of ovarian cancer patients, which was consistent with the KM-plot database." (PMID 34659572, 2021). "Similarly, KRT80 regulated by the miR-206/ETS1 axis plays a pivotal role in promoting tumor progression in ovarian cancer through the activation of the MEK/ERK signaling pathway." (PMID 40647481, 2025). "In ovarian cancer, miR-206 inhibited KRT80, suppressing the MEK/ERK signaling pathway." (PMID 38495507, 2024). "Furthermore, the Amniota-specific KRT8, KRT19, KRT23 and KRT80 were shown to be up-regulated in ovarian cancer." (PMID 36949761, 2023). "KRT80 expression is an independent prognostic factor in patients with ovarian cancer." (PMID 34659572, 2021). "This could be expanded in other cancer types, given that KRT80 clearly plays a role in ovarian cancer and other cancer types." (PMID 34659572, 2021). "Therefore, we speculate that miR-206/ETS1 regulates KRT80 to mediate the progression of ovarian cancer through the MEK/ERK pathway." (PMID 34659572, 2021). "Therefore, we concluded that KRT80 plays an important role in the development of ovarian cancer, and may be a prognostic indicator of ovarian cancer." (PMID 34659572, 2021). "Moreover, KRT80 expression was significantly correlated with clinical parameters, such as lymph node metastasis and pathological stage, in CRC and ovarian cancer." (PMID 36232922, 2022). "KRT80 overexpression stimulates the MEK/ERK signaling pathway and promotes the proliferation, G0/G1 phase to S phase transition, invasion, and migration of ovarian cancer cells." (PMID 34659572, 2021).
ovarian carcinoma (continued). "However, KRT80 expression in ovarian cancer, and its effect on malignant biological behavior, have not been reported." (PMID 34659572, 2021). "This neuronal or epithelial signature of ovarian carcinomas is raised from a rare cell type found in regular (non-tumoral) ovarian tissues which have a particular phenotype expressing Tyrosine hydroxylase, ChgA, the paraneoplastic protein PNMA1 and KRT80." (PMID 39592661, 2024). "Therefore, we speculate that miR-206 has no direct effect on KRT80, but through ETS1 which is a direct target of miR-206 in ovarian cancer cells." (PMID 34659572, 2021).